PAGE2B (PAGE family member 2B)
Synonyms: PAGE-2B; GAGEE3; CT16.5
Tractability: PROTAC: ubiquitination databases record sites on it.
Gene: Protein-coding gene on chromosome X (55,075,030 to 55,078,909, forward strand). Ensembl gene ENSG00000238269.
Homologues: Orthologues: macaque PAGE2B (92% identical), pig PAGE2B (51% identical). Paralogues in human: PAGE2 (94% identical), PAGE5 (88% identical), PAGE3 (43% identical), PAGE4 (41% identical), XAGE3 (37% identical), XAGE5 (36% identical), GAGE10 (33% identical), PAGE1 (33% identical), XAGE2 (32% identical), GAGE13 (32% identical), GAGE1 (31% identical), GAGE12C (31% identical), and 10 more.
Diseases named in the same sentence as PAGE2B in open-access papers:
PAGE2B is named in the same sentence as 7 diseases in open-access papers, as found by Europe PMC text mining. Sharing a sentence is not in itself a finding about the gene and the disease. The quoted sentences say what the papers report.
melanoma (2 papers, 2012 to 2016). A malignant, usually aggressive tumor composed of atypical, neoplastic melanocytes. "In particular, tumour antigen genes, such PAGE2B (prostate-associated P antigen family, member 2B), sarcoma antigen 1 (SAGE1) and several melanoma-associated antigens are overrepresented in the RGV regions." (PMID 27158822, 2016). "Importantly the melanoma cell lines used in this study did not express PAGE2B, the closest homolog to CT16." (PMID 23028975, 2012).
psychosis (2 papers, 2017 to 2021). "In conclusion, we found that a subgroup of patients with first-episode psychosis was seropositive to the N-terminal portion of the PAGE protein family (PAGE2B/PAGE2/PAGE5), and that such seropositivity was associated with the development of schizophrenia." (PMID 28742074, 2017). "Among the three types of autoantibodies with a significantly different distribution pattern in patients versus controls, autoantibodies toward the N-terminal portion of the PAGE protein family (PAGE2B/PAGE2/PAGE5) were exclusively seen in patients with first-episode psychosis." (PMID 28742074, 2017). "Autoantibodies toward a fragment of the PAGE2B (P antigen family, member 2B) protein, representing its N-terminal region, were observed in eight patients with first-episode psychosis, whereas no control subject presented with seropositivity toward the N-terminal fragment of PAGE2B." (PMID 28742074, 2017). "Additional studies are necessary to confirm these findings and to elucidate whether PAGE2B, PAGE2, PAGE5 or another protein cross-reactive to the N-terminal end of PAGE2B is the critical autoantibody target, and to further disentangle its role in the etiopathology of psychosis." (PMID 28742074, 2017).
schizophrenia (2 papers, 2017 to 2020). A major psychotic disorder characterized by abnormalities in the perception or expression of reality. "Both IPO13 and RIN3 showed a general high reactivity among all samples, while PAGE2B reactivity was observed in two schizophrenia subjects and two controls." (PMID 33208725, 2020).
Congenital dyserythropoietic anemia type IV (1 paper, 2024). Congenital dyserythropoietic anemia type IV (CDA IV) is a newly discovered form of CDA (see this term) characterized by ineffective erythropoiesis and hemolysis that leads to severe anemia at birth. "Genes BCAM linked to congenital dyserythropoietic anemia type IV and PAGE2B associated with recessive X-linked sideroblastic anemia were both up-regulated at R30 compared to baseline." (PMID 38740795, 2024).
ovarian insufficiency (1 paper, 2025). "Together, these data suggest FAM9C, ATP11C, and PAGE2B as potential candidate contributors to the ovarian insufficiency phenotype in TS and warrant further exploration." (PMID 40443572, 2025).
PAGE2B also shares sentences with these, for which no sentence is quoted: cancer (3 papers); X-linked sideroblastic anemia (1).